SLC60A2 (solute carrier family 60 member 2)
Description:
Low-affinity Na(+)-dependent glucose symporter with a Na(+) to glucose coupling ratio of 1:1. Potential channels for urea in the inner medulla of kidney.
Synonyms: KIAA1919; MFSD4B; NAGLT1; MGC33953
Tractability: Antibody: UniProt places it where antibodies can reach, with medium confidence; UniProt predicts a signal peptide or a membrane-spanning region; its Gene Ontology location is reachable by antibodies, with medium confidence. PROTAC: ubiquitination databases record sites on it.
Gene: Protein-coding gene on chromosome 6 (111,259,327 to 111,445,354, forward strand). Ensembl gene ENSG00000173214.
Subcellular location: Apical cell membrane
Pathways (Reactome):
Transport of small molecules: Cellular hexose transport
Gene Ontology:
Molecular function: protein binding; D-glucose:sodium symporter activity; transmembrane transporter activity
Biological process: D-glucose import across plasma membrane; sodium ion transmembrane transport; transmembrane transport
Cellular component: apical plasma membrane; brush border membrane
Genetic constraint (gnomAD): Loss-of-function variants: 7 observed, 8.16 expected, observed/expected ratio (o/e) 0.86, 90% interval 0.49 to 1.58. That is too few expected variants to judge how well the gene tolerates losing a copy. Missense variants: 524 observed, 596.5 expected, observed/expected ratio (o/e) 0.88, 90% interval 0.82 to 0.94. Synonymous variants: 200 observed, 222.07 expected, observed/expected ratio (o/e) 0.9, 90% interval 0.8 to 1.01.
Homologues: Orthologues: chimpanzee MFSD4B (99% identical), dog MFSD4B (83% identical), pig MFSD4B (82% identical), rat Mfsd4b1 (73% identical), mouse Mfsd4b4 (70% identical), rat Mfsd4b2l1 (64% identical), rat Mfsd4b2 (64% identical), mouse Mfsd4b1 (63% identical), rat Mfsd4b2l2 (63% identical), rat Naglt1 (62% identical), mouse Mfsd4b5 (61% identical), tropical clawed frog mfsd4b (52% identical), and 1 more. Paralogues in human: SLC60A1 (21% identical).
Diseases named in the same sentence as SLC60A2 in open-access papers:
SLC60A2 is named in the same sentence as 12 diseases in open-access papers, as found by Europe PMC text mining. Sharing a sentence is not in itself a finding about the gene and the disease.
SLC60A2 shares sentences with these, for which no sentence is quoted: cancer (2 papers); breast carcinoma (1); colorectal cancer (1); diabetes (1); infection (1); neuropathy (1); neurotoxicity (1); Obesity (1); psoriasis (1); rheumatoid arthritis (1); tumour (1); Vertigo (1).